MYCN (MYCN proto-oncogene, bHLH transcription factor)
Diseases named in the same sentence as MYCN in open-access papers (continued):
Sharing a sentence is not in itself a finding about the gene and the disease.
cancer (continued). "The Myc proto-oncogene family (MYC, MYCN, and MYCL) encodes three closely related transcription regulatory proteins that have been widely studied as critical mediators of a variety of cell functions, including dysregulated cell proliferation, metabolism, and survival in cancer." (PMID 38730731, 2024). "Therefore, targeting the complex formed by Aurora-A and MYCN directly could present a valuable strategy to modulate MYCN levels in cancer cells." (PMID 36601802, 2023). "Notably, well-known cancer-related TFs emerged, such as MYCN, GATA2, and ESR1." (PMID 37370684, 2023). "Thus, oncogenic MYCN levels globally suppress circRNA expression at least in part by aberrantly upregulating the DHX9 RNA helicase, suggesting that this may be a common mechanism in MYCN-driven cancers." (PMID 37402719, 2023). "However, CRLs are also present in SCF complex E3 ligases, which are recruited by RUNX3 to degrade oncoproteins GLI1, and likely MYCN, so potential cancer treatments may require a more personalized approach." (PMID 36899853, 2023). "Finally, we show that the workflow facilitates detection of larger circular DNA fragments containing extrachromosomal copies of the MYCN oncogene and the respective breakpoints, which is a potentially useful application in disease monitoring of several cancer types." (PMID 35711922, 2022). "detected copy number alterations in 4,577 human cancer samples representing nine different solid cancers and discovered that cell-derived enhancers were co-amplified with oncogenes in multiple solid tumors, including MYCN, which bore a compact relationship with drug resistance in medulloblastoma." (PMID 36793345, 2022). "Interestingly, MYCN can promote apoptosis and/or sensitizes cancer cells to cytotoxic drugs." (PMID 36139583, 2022). "Thus, our approach of specific MYCN targeting by BGA002 may result in the inhibition of the mTOR pathway only in cancer cells, leaving healthy cells unaffected." (PMID 35490242, 2022). "However, whether MYCN in NBL exerts a similar effect on immune regulation as MYC does in other cancers remains to be investigated." (PMID 33668573, 2021). "Indeed, since the high frequency of MYCN amplification in cancer and its role in driving and promoting tumorigenesis, as well as its space–temporal restricted expression during embryo development, precise N-Myc targeting would certainly result in successful therapeutics to support NB treatment." (PMID 34884690, 2021). "Moreover, apart from MNA, there are other cancer events that can lead to dysregulated N-Myc higher activity (mRNA and protein stabilization, mi-RNA alteration, and so on) making difficult to infer the MYCN relevance in these cases." (PMID 33718189, 2021). "However, the basis for the high MDM2 that drives MYCN expression in such cancers has been unclear." (PMID 33425720, 2020). "Inhibition of MYCNOS1 expression may be necessary to suppress MYCN activity when treating MYCN-amplified cancers without RB1 mutation." (PMID 33270844, 2020). "Importantly, Xia and colleagues reported the potential roles of the SGOC pathway based on their previous research in MYCN-amplified NB; these roles may be the hidden Achilles heel of all MYCN-driven cancers." (PMID 32034121, 2020). "Moreover, protein-coding MYCNOS2 facilitates the stabilization of MYCN oncoprotein, activation of Wnt/β-catenin signaling, and generation of an anti-apoptotic protein, which supports metastasis, chemoresistance, and survival of cancers." (PMID 33270844, 2020). "Moreover, upregulation of MYCN was observed in 71% (27/38) of cancer tissues." (PMID 32054830, 2020).
cancer (continued). "In addition, PRMT5 expression has correlated with MYC or MYCN protein in these cancers." (PMID 31694585, 2019). "Oncogenic transcription factors are notoriously difficult to target therapeutically, and the hypothesis that we tested in this investigation is whether subverting a MYCN-dependent genetic program could be used as a strategy in treating cancers driven by this protooncogene." (PMID 25477524, 2015). "Inhibition of MYCN expression would be desirable because of the “oncogene addiction” concept, i.e., cancer cells become dependent on an activated oncogene, and therefore suppression of the oncogene expression or activity could selectively impair cancer cell survival." (PMID 24515800, 2014). "Enhancement of MYCN expression might be also detrimental to cancer cells." (PMID 24515800, 2014). "Other oncogenes such as MYCN may more strongly induce ARID3B in human cancer." (PMID 22860069, 2012). "Together, these findings identify PA2G4 as a shared cofactor for both the c-MYC and MYCN oncoproteins and highlight its interaction with MYC family oncoproteins as a promising therapeutic vulnerability in MYC-driven cancers." (PMID 41002386, 2025). "Emerging evidence suggests that aberrant PUS7 activity contributes to disease states such as cancer, where it promotes oncogenic pathways including MYC/MYCN signaling, metabolic reprogramming, and cell proliferation." (PMID 40940790, 2025). "The c-MYC oncogenes family (MYC, MYCN, MYCL) plays a pivotal role in tumorigenesis, particularly in cancers characterized by MYC overexpression or amplification." (PMID 40710353, 2025). "Accordingly, abnormal regulation of genetic factors, such as NF-κB, MYCN, ALK, and Nrf2, has been constantly and similarly observed in various cancer types." (PMID 38666930, 2024). "Along with MYCN, other proto-oncogenes such as MYC and KRAS up-regulate components of the spliceosome in cancer, indicating a possible addiction to a hyperactivated spliceosome, and a potential novel therapeutic target." (PMID 38049564, 2024). "Our analysis revealed high expression of MYCN and downstream signature genes in HGSC compared to other cancer types." (PMID 38748789, 2024). "To determine the accuracy and LOD of amplifications, we tested reference materials with known copy numbers across six cancer driver genes (EGFR, ERBB2, FGFR3 MET, MYC and MYCN)." (PMID 39682116, 2024). "We propose a model in which MYCN and TSmiRs regulate U/FAS and play an important role in NB pathology, with implications for other MYC family-driven cancers." (PMID 38672672, 2024). "We propose a model in which MYCN and TSmiRs regulate UFAS and play an important role in NB, with implications for other MYC family-driven cancers." (PMID 38672672, 2024). "The effectiveness of CDK7 inhibition has been demonstrated in various aggressive cancer types, including small-cell lung cancer, triple-negative breast cancer (TNBC), MYCN-amplified neuroblastoma, osteosarcoma and pancreatic ductal adenocarcinoma." (PMID 38844984, 2024). "At this point, MYCN, ALK, RET and Phox2B built a complex network involved in different types of cancer, mostly involving the nervous system, also in regard to NF-κB (RelA/p65)." (PMID 38666930, 2024). "MiRNA host genes miR-22hg, miR-24hg, and miR-101hg appeared to be suppressed by both MYCN and MYC modulation, providing a possible mechanism for TSmiR suppression in NB and perhaps other MYC-driven cancers." (PMID 38672672, 2024). "Glutamine consumption is enhanced in cancer cells, and high expression of SLC1A5 (ASCT2), the major glutamine transporter, is correlated both to the levels of MYCN as well as the activating transcription factor 4 (ATF4) in NB cells." (PMID 39101440, 2024). "MYCN protein levels were higher, and its mRNA levels lower, in RAB27A-OE carcinoma cells than in the control ACHN cells." (PMID 38685086, 2024).
cancer (continued). "Among a global circRNA downregulation (408 circular transcripts) in MYCN-amplified samples, 25 circRNAs were upregulated, including CDR1-AS, the earliest studied circRNA in cancer." (PMID 37402719, 2023). "Our results reveal that ADAMTS9-AS2 promotes neuronal differentiation and inhibits cancer stemness by directly binding to LIN28B and modulating MYCN activity." (PMID 37991019, 2023). "Small cell lung cancer (SCLC) was the first cancer found to have amplification of all three members (c-MYC, L-MYC, and MYCN) of the MYC family of proto-oncogenes." (PMID 37046804, 2023). "Since it was first reported in 1965, an increasing number of ecDNAs have been found to carry important oncogenes in different types of cancer, including MYC, MYCN, and EGFR." (PMID 37217468, 2023). "The aberrant activity of the MYC family of transcription factors, which include c-MYC, MYCN, and MYCL, is frequently observed in cancer." (PMID 37760568, 2023). "MYCN, a member of the larger MYC family, regulates various cellular processes during development and in cancer." (PMID 37190157, 2023). "A well-defined source of circadian disruption in cancer is amplification of the MYC oncogene or its closely related paralogue MYCN (N-MYC), which leads to overexpression of MYC or N-MYC." (PMID 37639465, 2023). "Targeting the upstream regulators of MYCN, including HDACs and PI3K, was shown to suppress cancer growth." (PMID 35205815, 2022). "The Myc families of transcription factors (TFs), consisting of MYC, MYCN, and MYCL, are together the most commonly altered oncogenes in cancer." (PMID 36016998, 2022). "The prognostic signature that we constructed consisted of seven cancer driver genes (CDKN2C, HRAS, IRAK1, LOX, MYCN, NRAS, and PABPC1)." (PMID 36017503, 2022). "A future genomics profiling study, looking into the expression of the MYCN gene as well as other proto-oncogenes associated with defects in cell division and proliferation could further research into the potential connection between the abnormalities seen following SPC-μG exposure and cancer cells." (PMID 36430810, 2022). "All three aurora kinases, AURKA-C, serve oncogenic roles in cancer by promoting cell cycle progression, cancer cell survival, and promoting MYC/MYCN expression and activity." (PMID 33829040, 2021). "Among these strategies, anti-MYCN antigene oligonucleotide PNA showed the ability to specifically block MYCN expression in a sustained way, resulting in an anti-cancer effect." (PMID 33718189, 2021). "The oncoproteins, MYCN, MYC, and MYCL are short-lived transcription factors that are overexpressed or deregulated in more than half of all human cancer, making them attractive therapeutic targets." (PMID 33658627, 2021). "For the 33 cancers proposed by TCGA, we analyzed spearman’s correlation, p-value (2-sided t-test), and q-value (Benjamini-Hochberg FDR correction) of MYCN with indispensable genes in expression in different diseases sequentially." (PMID 33968733, 2021). "In fact, at least 28% of human cancers have amplified or translocated MYC, MYCN, or MYCL; in many more, MYC is upregulated downstream of other oncogenic insults." (PMID 34299381, 2021). "In cancer cells, MYC and MYCN exploit the ubiquitination pathway to stabilize aberrant oncogenic signaling and drive a wide variety of cellular processes required for carcinogenesis." (PMID 33767157, 2021). "Oncogenes like MYCN and ALK result in increased replication stress in cancer cells, offering therapeutically exploitable options." (PMID 34819497, 2021). "MCMs have also been implicated in the epithelial–mesenchymal transition and other well-known cancer cell signaling pathways, such WNT, CDK, MYCN, etc.." (PMID 34178990, 2021).
cancer (continued). "Other cancer amplified genes that also significantly increase ARE reporter activity are MYC (a previously known gene to exert post-transcriptional effect), MYCN, CCND1, CCNE1, SKP2, and NOTCH2." (PMID 34535639, 2021). "MYC proteins are often redundant in cancer and showing mutually exclusive expression patterns of MYC and MYCN in patient samples." (PMID 33585252, 2020). "MYC family oncoproteins MYC, MYCN, and MYCL are deregulated in diverse cancers and via diverse mechanisms." (PMID 33425720, 2020). "To extend our data to humans, we characterized the expression of MYCN, ATRX, and DAXX proteins across 12 human cancer cell lines." (PMID 32060267, 2020). "The prominent role of Myc family protooncogene transcription factors (TFs) (MYC, MYCN, MYCL) in the genesis of adult and childhood cancers makes these TFs attractive targets for drug discovery and development." (PMID 33016930, 2020). "Taken together, HOXD-AS1 serves as a cancer-promoting gene, and SP1/HOXD-AS1/miR-520c-3p/MYCN pathway exerts vital regulatory function in initiation and progression of CCA." (PMID 32857725, 2020). "TWIST1 and ADAM22 were also positively correlated with cancer stage, while GAL was an independent OS predictor in addition to MYCN and age." (PMID 32629858, 2020). "In turn, stabilized N-MYC directly enhances the transcription of PLK1, forming a positive feedforward regulatory loop that reinforces the progress of MYCN-driven cancers." (PMID 33614505, 2020). "If MYCN amplification event occurs in the PCA stage (~ 5% PCA patients), ADT treatment would kill most of androgen-responsive cancer cells but still induce a proliferation-arresting status (senescence) in a significant subpopulation." (PMID 30657058, 2019). "Aberrant up-regulation of any MYC family member (MYC, MYCN, or MYCL) promotes metabolic reprograming that leads to sustained proliferation of cancer cells." (PMID 31416966, 2019). "Several studies also demonstrate protein/protein interactions of C-Myc or MYCN (together referred to as Myc(N)) with LSD1, that alter expression of critical cancer related genes." (PMID 29755654, 2018). "Inhibition of PERK reduces autophagy in MYCN amplified NB cells, thus amplifying the efficacy of the GLI inhibitor GANT-61 in reducing proliferation of this type of cancer cells." (PMID 29581853, 2018). "RKIP directly inhibits key cancer-promoting kinases such as GRK2, Rac, and GSK3β, and these kinases can regulate MYCN expression through Raf-independent mechanisms." (PMID 28187004, 2017). "For instance, eIF2 signaling was among the top canonical pathways both for BPA and BPF; ESR1, MYCN or MYC were found as upstream regulators; and “cancer” as well as “organismal injury and abnormalities” were shared between the three products." (PMID 28628672, 2017). "Based on these findings, we investigated the relationship between MYCN or MYC and SGO1/SGO2 expression levels using The Cancer Genome Atlas (TCGA) pan-cancer gene expression datasets." (PMID 27539729, 2016). "More than 40 % of the DEGs (32 out of 79 genes) have been proven to have prognostic values with at least one type of cancer, including well-known oncogenes RHEB and MYCN." (PMID 27769251, 2016). "JQ1 is known to induce growth suppression by transcriptional inhibition of numerous genes, including MYC, MYCN and ASCL1, in human cancer cells." (PMID 27764802, 2016). "MYC proto-oncogenes (MYC, MYCN, MYCL) are transcription factors that play key roles in both normal development and cancer." (PMID 25294817, 2015). "Several lines of evidence have also pointed to an intricate link of MYCN with proteins of the cell cycle machinery, resulting in synthetic lethality of CDK inhibition in MYC(N)-dependent cancers." (PMID 26029996, 2015).
cancer (continued). "These miRNAs target the tumour suppressor genes, PTEN, TP53INP1 and TP53INP2, and other proteins involved in cancer development and progression, such as BCL2L2, ERBB4, MAPK9, MCL1, MYCN, VEGFA and VEGFR1." (PMID 20668671, 2010). "Importantly, recent studies have shown that MYCN and MYCL are also expressed in other cancers, driving tumor development." (PMID 40732268, 2025). "After treating BLCA cells with gemcitabine, the expression of MYCN and PKIB decreased over time, while the expression of p-HSP27 increased gradually, consistent with the inhibitory effects of these protein expression changes on cancer cells." (PMID 40593489, 2025). "The MYC gene family, consisting of MYC (also known as C-Myc), MYCN (N-Myc), and MYCL1 (LMYC), plays a significant role in promoting epidermal differentiation, cell proliferation, apoptosis, and the development of specific human cancers." (PMID 38566927, 2024). "Similarly, in cancer cells, proteins like ELF3, MYCN, and TGIF1 engage in comparable self-sustaining loops within SE domains, propelling the transcription of essential oncogenic TFs and their associated genes." (PMID 38844984, 2024). "A drug toxicity test in healthy PBMCs revealed lower sensitivity to ceftriaxone compared with MYCN‐amplified cancer cells but similar sensitivity to MYCN‐nonamplified cancer cells, as indicated by the IC50 values." (PMID 37975412, 2024). "It is also possible that U/FAS gene expression levels in cancer are, in part, regulated indirectly by MYC and MYCN through transcriptional suppression of TSmiR host gene expression and consequent release of U/FAS mRNAs from post-transcriptional TSmiR-mediated degradation." (PMID 38672672, 2024). "On the basis of drug screening data obtained from the Genomics of Drug Sensitivity in Cancer (GDSC) and Cancer Therapeutics Response Portal (CTRP) databases, we observed similar results for cell lines with ecMYC and ecDNA containing MYCN that were sensitive to type I AURKi." (PMID 37217468, 2023). "MYCN is a common oncogene in many types of cancers, yet how MYCN regulates global gene expression has not been well-characterized." (PMID 37781575, 2023). "Three myc family genes, MYC, MYCN, and MYCL, are found in ecDNA in various cancers." (PMID 37217468, 2023). "Moreover, focal CNA amplifications encompassed genomic peaks that harbored canonical cancer genes including those found at HPV-integrated hotspots (MYC, MYCN, MYCL, SOX2, NR4A2, and ANKRD12), and others (CCNE1, SMAD2, BCL2L1, and GNAS)." (PMID 36216793, 2022). "CDK7 might also be an attractive target in MYC‐driven tumors: indeed, the covalent CDK7 inhibitor THZ1 disproportionally repressed super‐enhancer regulated genes, including MYC, MYCN and MYCL in diverse cancer‐derived cell lines." (PMID 36214609, 2022). "Furthermore, MYCN mRNA levels were correlated with ALK expression, supporting the notion that ALK and MYCN cooperate in cancer progression." (PMID 36337169, 2022). "We cannot exclude “off target” anti-cancer effects of the combination therapy which do not involve MYCN and USP5." (PMID 33658627, 2021). "Indirect targeting of MYCN using small molecule inhibitors such as bromodomain inhibitors and inhibitors that disrupt the interaction between MYC and its binding partner, MAX has been explored in different cancers." (PMID 34680394, 2021). "PIK3CA-mutant cancers displayed higher expression of 12 of the 17 Wnt genes compared to PIK3CA wild-type tumors, including five Wnt target genes (LEF1, MYCN, FZD7, SFRP2, and TNFRSF11B) and seven Wnt signaling components (TCF7L1, TCF7L2, CTNNB1, FZD4, SFRP1, WNT5A, and MSX2)." (PMID 34035258, 2021). "Remarkably, N-myc levels closely correlated with the expression of all these genes in NB and all but lif in neuronal progenitors, confirming the role of MYCN in the maintenance of pluripotency features also in cancer cells." (PMID 34771690, 2021).